LY6E (lymphocyte antigen 6 family member E)
Diseases named in the same sentence as LY6E in open-access papers (continued):
Sharing a sentence is not in itself a finding about the gene and the disease.
COVID-19 (5 papers, 2021 to 2023). A disease caused by infection with severe acute respiratory syndrome coronavirus 2. "Therefore, the reduced expression of the LY6E gene in nasal macrophages of samples with COVID-19 vaccination may be due to the fact that COVID-19 vaccination helped to avoid SARS-CoV-2 attack on the nasal cavity." (PMID 37007947, 2023). "Conventional ISGs, such as IFI6, IFI44L, LY6E, and ISG15, were markedly increased in COVID-19 patients compared to healthy controls across all major cell types in PBMCs." (PMID 35064122, 2022). "Comparison of severe and mild Symptomatic COVID-19 cases revealed an upregulation of CD177, the neutrophil marker, CXCL16, MAPKMAPK2 and IRF2BP2 with downregulation of ISGs; IFIT, IFIT3, OAS1, OAS2, LY6E and MX1 in severe cases." (PMID 34824360, 2021).
gastric cancer (5 papers, 2016 to 2024). A primary or metastatic malignant neoplasm involving the stomach. "The survival data for colorectal, ovarian and gastric cancer showed that all four studied genes Ly6D, Ly6E, Ly6H, Ly6K are poor prognosis markers for multiple cancer types." (PMID 26862846, 2016). "High Ly6E mRNA expression in gastric cancer was significantly correlated with decreased five-year metastasis free survival (metastasis, n=11 vs metastasis free, n=7), decreased one-year overall survival (dead, n=12 vs alive, n=34) in Forster and Chen studies." (PMID 26862846, 2016). "Ly6E mRNA expression was significantly increased in gastric cancer (n=89) than normal tissues (n=62) in D'Errico, Cho and Wang studies." (PMID 26862846, 2016). "LY6E expressions are increased in bladder cancer, gastric cancer, etc.." (PMID 35123499, 2022). "Notably, inhibition of LY6E with siRNA was shown to restore PTEN expression, induce G1-S phase cell cycle arrest, and increase apoptosis in gastric cancer, suggesting that LY6E’s inhibition may be enough to cause anti-tumor effects in some cancers." (PMID 33613843, 2021). "High Ly6H mRNA expression in gastric cancer was significantly correlated with poor five-year first progression free survival (low Ly6H, n=336; high Ly6E, n=499; HR=1.5, p=6.9E-05) and five-year overall survival (low Ly6H, n=377; high Ly6E, n=499; HR=1.56, p=6E-07) shown by KM plotter." (PMID 26862846, 2016).
HIV-1 infection (5 papers, 2019 to 2025). The type species of lentivirus and the etiologic agent of acquired immunodeficiency syndrome (AIDS). "LY6E was shown to differentially regulate HIV-1 infection depending on cell surface CD4 expression levels." (PMID 35333911, 2022). "Altogether, these results strongly suggest that LY6E contributes to the promotion of cell-free HIV-1 infection by IFN-α." (PMID 35468127, 2022). "Instead, LY6E was reported to promote the infection of enveloped RNA viruses from several viral families and modulates HIV-1 infection in a manner dependent on the level of CD4 expression in target cells." (PMID 32641482, 2020). "Yu and colleagues elegantly demonstrated recently that LY6E enhances HIV-1 infection of CD4+ T cells and monocytic THP1 cells by promoting the expansion of viral fusion pores induced by HIV-1 Env." (PMID 32641482, 2020). "We recently explored the direct role of LY6E in HIV-1 infection, particularly at the early stage of viral replication." (PMID 31684192, 2019). "Somewhat surprisingly, we recently uncovered a new yet distinct effect of LY6E on HIV-1 infection in low CD4-expressing T cells." (PMID 31684192, 2019). "Finally, the single-round infection experiments using different densities of viruses and cells showed that the enhancement of HIV-1 infection by IFN-α treatment at a high density is abolished by LY6E KO." (PMID 35468127, 2022). "Moreover, to investigate the effect of endogenous LY6E on HIV-1 infection, we prepared LY6E knock-out (KO) Jurkat-CCR5 cells using the CRISPR/Cas9 system." (PMID 35468127, 2022). "To assess whether LY6E can contribute to the enhancement of cell-free HIV-1 infection, we prepared a Jurkat cell line transduced with HA-tagged LY6E (Jurkat/LY6E-HA)." (PMID 35468127, 2022). "As an ISG, LY6E has been shown to enhance the infection of Dengue virus, ZIKV, yellow fever virus, IAV, and VSV, while having dual effects on HIV-1 infection, promoting infection in CD4-high T cells and inhibiting it in CD4-low T cells." (PMID 40901862, 2025). "We further demonstrate that LY6E, an IFN-stimulated gene, can contribute to the density-dependent enhancement of cell-free HIV-1 infection." (PMID 35468127, 2022). "We also revealed that an ISG, LY6E, is up-regulated by IFN-α treatment and promotes HIV-1 infection." (PMID 35468127, 2022).
lung carcinoma (5 papers, 2016 to 2025). "The LY6 family, consisting of Ly6D, Ly6E, Ly6K and Ly6H, is also associated with poor survival in several cancer types, including lung cancer." (PMID 35574342, 2022). "This discovery marks the pioneering evidence linking α5-nAChR and Ly6E expression in lung carcinogenesis, positioning these molecules as promising targets for the lung cancer-specific therapies." (PMID 40143965, 2025). "The collaboration between Ly6E and α5-nAChR in lung cancer directs TGF-β1/Smad3 signaling, modulating neoplasms migration." (PMID 40143965, 2025). "Survival data for breast and lung cancer show that Ly6D, Ly6E and Ly6K were poor prognosis marker for these cancers." (PMID 26862846, 2016). "Notably, nicotine elicits an upregulation of α5-nAChR, Ly6E, phosphorylated Smad3 (pSmad3), Zeb1, N-calmodulin, and vimentin in lung cancer cells." (PMID 40143965, 2025). "This process involves nicotine activates to α5-nAChR on the cell surface, subsequent interaction with Ly6E, and activates TGF-β1/Smad signaling to promote lung cancer cell motility." (PMID 40143965, 2025).
colorectal cancer (4 papers, 2011 to 2022). A primary or metastatic malignant neoplasm that affects the colon or rectum. "In this study, we analyzed the differences in LY6E expression in colorectal cancer and other types of cancer." (PMID 35310607, 2022). "Ly6E mRNA expression was significantly increased in colorectal cancer (n=10) than normal tissues (n=5) in Skrzypczak study." (PMID 26862846, 2016). "High Ly6H mRNA expression in colorectal cancer was significantly correlated with poor five-year relapse free survival (low Ly6H, n=70; high Ly6E, n=70; HR=7.6, p=0.0326, n= number of patient, HR=hazard ratio) shown by PROGgeneV2." (PMID 26862846, 2016). "However, the biological role of LY6E in colorectal cancer (CRC) remains largely unknown." (PMID 35310607, 2022). "In contrast, LY6E, the other gene found as upregulated in ASD blood samples, was suggested as a biomarker of poor prognosis in smoking-induced lung carcinogenesis and colorectal cancer." (PMID 36077244, 2022).
hepatocellular carcinoma (4 papers, 2018 to 2024). A malignant tumor that arises from hepatocytes. "Meanwhile, ectopic LY6E expression in human lung malignant adenoma (A549), human hepatoma (Huh7.5), human embryonic kidney (HEK293T), or Syrian infant hamster kidney (BHK) cells does not enhance YFV replication." (PMID 38169284, 2024). "Ectopic LY6E expression in human lung adenocarcinoma cells (A549), human hepatoma cells (Huh7.5), human embryonic kidney cells (HEK293T), or Syrian baby hamster kidney cells (BHK) did not enhance YFV." (PMID 30190477, 2018).
glioma (3 papers, 2016 to 2024). A benign or malignant brain and spinal cord tumor that arises from glial cells (astrocytes, oligodendrocytes, ependymal cells). "High Ly6E mRNA expression in glioma was significantly correlated with poor five-year overall survival (low Ly6E, n=14; high Ly6E, n=14; HR=2.34, p=0.0026, n= number of patient, HR=hazard ratio), shown by PROGgeneV2." (PMID 26862846, 2016). "Survival data for bladder and brain and CNS cancer showed that Ly6E and Ly6K is poor prognosis marker for these cancers." (PMID 26862846, 2016). "These miR-637-targeted genes include HMGA1, CDK6, and WNT7A in glioma, HEMGN in PTC, APLN in GC, USP21 in HCC, LY6E and CTSB in CHOL, NUPR1 in OSCC and MM, HDAC4 in SaOS, ABL1 in CML, KLK4 in OC, PLXNB2 in OC, AKT1 in TNBC, PTC, and HCC, AKT3 in TNBC, and RING1 in CCa." (PMID 36175921, 2022). "These genes include HMGA1 in glioma, AKT1 in glioma, PTC, GC, and HCC, HEMGN in PTC, APLN and MMP19 in GC, WNT1 in CRC, NUPR1 in CRC and OSCC, LY6E and CTSB in CHOL, KLK4 and PLXNB2 in OC, and HDAC4 and STAT3 in SaOS." (PMID 36175921, 2022).
non-small cell lung carcinoma (3 papers, 2023 to 2024). A group of at least three distinct histological types of lung cancer, including non-small cell squamous cell carcinoma, adenocarcinoma, and large cell carcinoma. "The interaction between CHRNA5 and Ly6E mediates the migration of non-small cell lung cancer cells through the TGF-β1–Smad signalling pathway." (PMID 38879667, 2024). "This is similar to a previous finding where the knockdown of LY6E inhibited EMT in non-small-cell lung cancer cells." (PMID 38067506, 2023).
ovarian carcinoma (3 papers, 2016 to 2024). A malignant neoplasm originating from the surface ovarian epithelium. "PUF60, Rad21, and LY6E are genes located on chromosome 8q24, an important locus associated with the progression of ovarian cancer and amplified region in around 14% of ovarian tumors." (PMID 39408764, 2024). "Moreover, PUF60, Rad21, and LY6E are located on chromosome 8q24, a locus often amplified and associated with the progression of ovarian cancer." (PMID 39408764, 2024). "Finally, LY6E emerges as a promising prognostic biomarker, with its amplification correlating with worse overall survival in ovarian cancer patients and its association with immune signatures suggesting a potential role in predicting response to ICB therapy." (PMID 39408764, 2024). "Overall, our study provides novel insights into the molecular determinants of PARPi resistance and highlights LY6E as a promising prognostic biomarker in the management of HRD ovarian cancer." (PMID 39408764, 2024). "Our analysis shows that across all tumor types, ovarian cancer presents the highest LY6E expression (GEPIA2)." (PMID 39408764, 2024). "Ly6E mRNA expression was significantly increased in ovarian cancer (n=396) than normal tissues (n=40) in Yoshihara, Adib, TCGA (NCI, unpublished), Welsh, Bonome and Henedrix studies." (PMID 26862846, 2016). "We present compelling evidence implicating LY6E (lymphocyte antigen 6 complex, locus E; aliases RIGE; SCA2; RIG-E; SCA-2; TSA-1), a member of the Ly-6/uPAR protein family and is a critical mediator of PARPi resistance in BRCA1-deficient ovarian cancer." (PMID 39408764, 2024). "Furthermore, our analysis of Orien/cBioPortal data reveals a prognostic implication of LY6E amplification in ovarian cancer, suggesting its potential utility as a biomarker for patient stratification and therapeutic decisions." (PMID 39408764, 2024). "Additionally, ovarian cancer patients with high CNV copies and high gene expression of LY6E present a worse OS (Log rank p-value 0.02)." (PMID 39408764, 2024). "Additionally, the gene expression of LY6E is related to the expression of RAD21 and PUF60, both genes are located at chromosome 8q24, a loci frequently amplified in ovarian cancer." (PMID 39408764, 2024).
bladder cancer (2 papers, 2016 to 2022). "The gene expression analysis showed that bladder cancer expresses significant high levels of Ly6D, Ly6E, Ly6K." (PMID 26862846, 2016). "Ly6E mRNA expression was significantly higher in superficial bladder cancer (n=28) than infiltrating bladder cancer (n=81) and high expression of Ly6E was correlated with higher grade (infiltrating grade 3, n=75 vs infiltrating grade 2, n=6) in Sanchez-Carbayo study." (PMID 26862846, 2016).
cholangiocarcinoma (2 papers, 2021 to 2022). A carcinoma that arises from the intrahepatic biliary tree (intrahepatic cholangiocarcinoma) or from the junction, or adjacent to the junction, of the right and left hepatic ducts (hilar cholangiocarcinoma). "In Cholangiocarcinoma (CCA), circ-0000284 (circHIPK3) was found to elevate lymphocyte antigen 6E (LY6E) expression by competitively binding miR-637Owing to circRNAs that are enriched and stable in exosomes." (PMID 34234872, 2021).
colon cancer (2 papers, 2022 to 2023). "The presence of LY6E and LY6E-associated ceRNA expression was confirmed via qRT-PCR in colon cancer cells." (PMID 35310607, 2022).
melanoma (2 papers, 2016 to 2024). A malignant, usually aggressive tumor composed of atypical, neoplastic melanocytes. "Ly6E mRNA expression was significantly increased in melanoma (n=45) than normal skin (n=7) in Talantov study." (PMID 26862846, 2016). "We used mRNA expression of the type I IFN-responsive genes Ly6E, MX1, IFI44L and IFITM1 to determine the pre-treatment type I IFN score in the PBMCs from the melanoma patients in our study." (PMID 38967829, 2024).
neuroblastoma (2 papers, 2016 to 2026). Neuroblastoma (NB) is the most common solid, extracranial childhood tumor. "Six of these genes (CMBL, LY6E, KLRB1, CTSH, CD3D, and PTGDS) were utilized to construct a risk-scoring model that effectively stratified neuroblastoma patients into high- and low-risk groups with significantly distinct clinical outcomes (p < 0.001)." (PMID 41993132, 2026). "High Ly6E mRNA expression in neuroblastoma was significantly correlated with five-year recurrence free survival (recurrence, n=46 vs no recurrence, n=56) in Asgharzadeh study." (PMID 26862846, 2016). "More importantly, we revealed that LY6E modulates M2-type macrophage polarization in neuroblastoma for the first time, suggesting a novel mechanism through which it may contribute to shaping an immunosuppressive tumor microenvironment." (PMID 41993132, 2026).
age (1 paper, 2024). A temporal measurement of the time period elapsed since an identifiable point in the life cycle of an organism. "The interplay between NFκB, PDGF-BB, LY6E, ID3, PTP4A1, and FOS in age-related vascular endothelial dysfunction and related pathologies underscores the complexity of molecular mechanisms governing vascular health." (PMID 38674087, 2024).
AIDS (1 paper, 2019). A syndrome resulting from the acquired deficiency of cellular immunity caused by the human immunodeficiency virus (HIV). "The opposing effect of LY6E on HIV infection may have implications for understanding the role of LY6E in the early stage of HIV transmission in monocytes/MDMs/DCs, where CD4 expression is low, in contrast to the late stage of AIDS pathogenesis where the virus predominantly infects high-CD4 T cells." (PMID 31684192, 2019).
atherosclerosis (1 paper, 2023). A disease characterized by the build-up of fatty material and calcium deposition in the arterial wall resulting in partial or complete occlusion of the arterial lumen. "The expression of LY6E has been found in atherosclerosis-susceptible white carneau aortic smooth muscle cells." (PMID 37662558, 2023).
cervical cancer (1 paper, 2016). A primary or metastatic malignant neoplasm involving the cervix. "Ly6E mRNA expression was significantly increased in cervical cancer (n=90) than normal tissues (n=34) in Scotto, Pyeon and Biewenga studies." (PMID 26862846, 2016).
embryonic cancer (1 paper, 2016). "Ly6E mRNA expression was significantly increased in embryonic tumors (n=24) than normal testis (n=6) in Korkola study and pleural malignant mesothelioma (n=40) than normal samples (n=9) of pleura in Gordon study." (PMID 26862846, 2016).
esophageal cancer (1 paper, 2016). A primary or metastatic malignant neoplasm involving the esophagus. "Ly6E mRNA expression was significantly higher in esophageal cancer (n=83) than precursor (n=23) in Kimchi and Su studies." (PMID 26862846, 2016). "Ly6E mRNA expression was significantly increased in esophageal cancer (n=78) than normal tissues (n=78) in Kimchi, Hu and Su studies." (PMID 26862846, 2016).
head and neck cancer (1 paper, 2016). A primary or metastatic malignant neoplasm affecting the head and neck. "Ly6E mRNA expression was significantly increased in head and neck cancer (n=396) than normal tissues (n=17) Toruner, Giordano, Ye, Peng, Peng 2, He, Cromer, Estilo, Vasko, Ginos and Frierson studies." (PMID 26862846, 2016).
hemorrhagic fever (1 paper, 2018). An infectious disease caused by certain viruses or bacteria that can damage the walls of tiny blood vessels, making them leak, and can hamper the blood's ability to clot and cause severe, life-threatening illness. "Importantly, Ly6e transcripts were enriched in LASV-infected human peripheral blood mononuclear cells (PBMCs), as well as in other hemorrhagic fevers." (PMID 29724035, 2018).
kidney cancer (1 paper, 2016). Primary or metastatic malignant neoplasm involving the kidney. "Ly6E mRNA expression was significantly increased in kidney cancer (n=155) than normal tissues (n=68) in Yusenko, Beroukhim, Jones, Cutcliffe, Gumz, and Lenburg studies." (PMID 26862846, 2016).
leukaemia (1 paper, 2025). "Further analysis identified Ly6A as a driver of NK cell–mediated immune evasion of mouse leukaemia and extended our knowledge about the role of human LY6E in limiting NK cell antitumour activity." (PMID 39642167, 2025). "Translation of our findings to the human system showed that high expression of LY6E on tumour cells impaired their physical interaction with NK cells and led to worse prognosis in leukaemia patients." (PMID 39642167, 2025).
multiple myeloma (1 paper, 2025). "Here, we finally obtained the multiple myeloma-related bone disease gene LY6E through a series of cohorts based on the DEGs of MM datebases." (PMID 40180998, 2025).
nephritis (1 paper, 2014). Inflammation of renal tissue. "Fabp4, Gsn, Il6st, and Ly6e, were associated with nephritis and Col18a1, Prom1, and Scd1 with renal cell carcinoma." (PMID 25409434, 2014).
ovarian tumors (1 paper, 2024). "The LY6E gene is mutated in 32% of ovarian tumors in the cBioPortal (total 1018 patients and 2141 samples) and amplification is the most common mutation, which is reflected in increasing mRNA expression." (PMID 39408764, 2024). "Further investigations into the functional implications of LY6E as a prognostic biomarker for HRD-resistant ovarian tumors are warranted to translate them into clinical applications and improve patient outcomes." (PMID 39408764, 2024).
pancreatic ductal adenocarcinoma (1 paper, 2022). An infiltrating adenocarcinoma that arises from the epithelial cells of the pancreas. "Recent data suggest that increased expression of LY6E is associated with poor overall survival of renal papillary cell carcinoma and pancreatic ductal adenocarcinoma." (PMID 35123499, 2022).
prostate carcinoma (1 paper, 2016). A carcinoma that arises from epithelial cells of the prostate gland. "Ly6E mRNA expression was significantly increased in prostate cancer (n=36) than normal tissues (n=17) in Tomlins study." (PMID 26862846, 2016). "This analysis showed that four different members Ly6D, Ly6E, Ly6H or Ly6K have increased gene expressed in bladder, brain and CNS, breast, colorectal, cervical, ovarian, lung, head and neck, pancreatic and prostate cancer than their normal counter part tissues." (PMID 26862846, 2016).
Sepsis (1 paper, 2019). Sepsis is defined as life-threatening organ dysfunction caused by a dysregulated host response to infection. "We identified 687 differentially expressed genes between ARDS and ARDS-HSCT (adjusted p-value < 0.01), including IFI44L, OAS3, LY6E, and SPATS2L that had increased expression in ARDS vs. ARDS-HSCT; these genes were not differentially expressed in sepsis vs sepsis-HSCT." (PMID 30665420, 2019).
skin cancer (1 paper, 2016). "We confirmed that the expression of LY6E positively correlated with poor overall survival rates in several human cancer patients including lung, bladder, brain, and skin cancers." (PMID 27589564, 2016). "Moreover, we confirmed that LY6E expression levels in malignant tumors correlated with the poor overall survival of patients with various cancers including lung, bladder, brain, and skin cancers." (PMID 27589564, 2016).